RASAL2 (RAS protein activator like 2)
Diseases named in the same sentence as RASAL2 in open-access papers (continued):
Sharing a sentence is not in itself a finding about the gene and the disease.
tumor (continued). "Rasal2 is originally considered as a tumor-suppressor via its regulation of Wnt, Hippo and Ras signaling pathways." (PMID 35044284, 2022). "Early studies identified RASAL2 as a tumor suppressor, with a notion mostly inferring from findings on tumor angiogenesis and metastasis." (PMID 35844783, 2022). "Enrichment analysis showed four differential expression genes (DEGs) related to tumor growth pathways RASAL2, SerpinB5, UTG1A4, and PDE3A." (PMID 36159573, 2022). "As a unique member of the RAS-GAP family, RASAL2 has been found to have inconsistent roles across different tumours in previous studies." (PMID 35668070, 2022). "Mechanistically, we found that RASAL2 promoted tumour cell proliferation, the transition from G1 to S phase in vitro and tumour growth in vivo." (PMID 35668070, 2022). "RASAL2 promoted tumor cell proliferation, migration and invasion in PDAC cells in vitro and growth and metastasis in animal models." (PMID 35844783, 2022). "Conversely, knockdown of TIAM1 in RASAL2-overexpressing MIA PaCa-2 cells with siRNA reduced the ability of tumor cell proliferation, migration and invasion." (PMID 35844783, 2022). "In the present study, we demonstrated that RASAL2 was an oncogene in PCa that promoted PCa cell proliferation and tumour growth through the PI3K/AKT/cyclin D1 signalling pathway." (PMID 35668070, 2022). "Taken together, our data demonstrates tumor suppressor role for RASAL2 in human PCa cells, despite increased RAS oncogenic activity." (PMID 34966481, 2021). "The mammalian homologs of Raskol, Rasal2 and Dab2IP, were identified in a screen for RasGAP tumour suppressors and are frequently downregulated in multiple types of cancer cells." (PMID 30763317, 2019). "RASAL2 plays a critical role in inhibiting tumor angiogenesis, which means that it can act as a tumor suppressor." (PMID 31799194, 2019). "RASAL2 exhibits different relationship with clinical cancer stage, histological grade, prognosis and overall survival in different kinds of tumor." (PMID 31799194, 2019). "We further assessed RASAL2 mRNA expression in 18 pairs of primary tumor and matched adjacent normal tissues." (PMID 30037330, 2018). "To be more important, after analyzing RASAL2 level in patients from TCGA cohort, we found that RASAL2 was inversely correlated with tumor stages and grades." (PMID 30158581, 2018). "Herein, we identify RASAL2 as a novel tumor suppressor in RCC, and it can inhibit RCC angiogenesis via p-GSK3β/c-FOS/VEGFA pathway." (PMID 30158581, 2018). "We noticed that RASAL2 overexpression leaded to a reduced tumor weight and volume in comparison to control." (PMID 30158581, 2018). "We further employed gene expression microarrays to identify genes differentially expressed among primary tumor, metastasis and normal colon mucosa samples, one of which was RASAL2." (PMID 30037330, 2018). "In vitro and in vivo functional studies revealed that RASAL2 promoted tumor progression in both KRAS/NRAS mutant and wild-type CRC cells." (PMID 30037330, 2018). "To strengthen the tumor-suppressor role of RASAL2 in RCC angiogenesis, we examine the association of RASAL2 and tumor angiogenesis in our clinical samples." (PMID 30158581, 2018). "Our findings appear to contradict a previous finding that RASAL2 was a tumor suppressor whose downregulation resulted in increased tumor growth, progression and metastasis in CRC." (PMID 30037330, 2018). "Herein, we provide evidence that RASAL2 acts as a tumor suppressor in BCa, and modulates the phenotypes of cancer stemness and EMT through MAPK/SOX2 pathway." (PMID 28182001, 2017). "We found that the expression of RASAL2 protein was not only lower in BCa tissues than normal epithelia, but also negatively correlated with tumor grades (*P<0.05, **P<0.01)." (PMID 28182001, 2017). "Taken together, our data indicate that RASAL2 is a tumor suppressor in BCa, and modulates cancer stemness and EMT for BCa recurrence and metastasis." (PMID 28182001, 2017).
tumor (continued). "To further verify the tumor-suppressive role of RASAL2 in BCa in vivo, we established the subcutaneous xenograft using 5637 sublines." (PMID 28182001, 2017). "We observed that RASAL2 downregulation resulted in an increased tumor weight and size compared with control." (PMID 28182001, 2017). "Up-regulation of RASAL2 was also observed, which was recently reported as a tumor and metastasis suppressor." (PMID 25646775, 2015). "Higher levels of phospho-ERK1/2, phospho-MEK1/2 and phosphor-Raf-1 were consistently observed in RASAL2 knockdown tumor samples." (PMID 25216515, 2014). "RASAL2 suppression resulted in a significant increase in the number of tumor nodules and tumor weight compared with scramble." (PMID 25216515, 2014). "As a RAS-GAP, RASAL2 is a known tumour suppressor in a number of cancer types." (PMID 39890967, 2025). "Consequently, RASAL2-high tumour cells are able to withstand chemotherapy-induced apoptosis, effectively evading cell death." (PMID 39890967, 2025). "While the role of RASAL2 in fish remains unclear, in mammals, it has been characterized as a tumor and metastasis suppressor." (PMID 41165328, 2025). "In TNBC, miR-136 has been shown to act as a tumor suppressor by directly targeting RASAL2." (PMID 40104500, 2025). "Furthermore, we observed that RASAL2 protein was enriched in post-treatment (residual) TNBC tumour tissue compared to patient-matched adjacent normal breast tissue." (PMID 39890967, 2025). "Additionally, genetically engineered RASAL2 knockout mice are prone to several sporadic tumours, including LUAD." (PMID 36420686, 2022). "Recent studies showed that RASAL2 promoted malignancy of tumor cells." (PMID 35844783, 2022). "Rasal2 can also exerts pro-tumor effect in several types of cancer." (PMID 35044284, 2022). "Similarly, RASAL2 mRNA levels were elevated in tumour tissues in datasets from the GEO and Oncomine databases." (PMID 35668070, 2022). "Knockdown of RASAL2 decreased tumour volume and weight compared to the control group." (PMID 35668070, 2022). "For instance, RASAL2 inhibits tumor cell migration and invasion by inactivating the RAS pathway." (PMID 34430085, 2021). "Mechanistically, a crosstalk between TNFα and RASAL2 in PCa may provide a new insight into RASAL2 signal transduction in modulating the tumor microenvironment." (PMID 34966481, 2021). "Consequently, one of the mechanisms for the different expression levels of RASAL2 in different tumor types was due to the methylation status of RASAL2 promoter." (PMID 30158581, 2018). "RASAL2 proteins were predominantly cytoplasmic in the tumor cells." (PMID 30037330, 2018). "Thus, in addition to dampening apoptotic signalling, it is conceivable that being a RAS GAP RASAL2 may further bolster the anti-apoptotic ability of tumour cells by directly attenuating mitochondrial RAS pro-apoptotic signalling." (PMID 39890967, 2025). "Furthermore, an in vivo studies on tumor xenografts, where BxPC-3 cells were transfected with miR-135b-3p mimics, resulted in decreased tumor size that correlated with overexpression of miR-135b-3p and RASAL2." (PMID 38596245, 2023). "For rs12028023 in RAS protein activator‐like 2 (RASAL2), we studied its effect by MAPK pathway activation status (by comparing to 760 patients without MAPK‐activated CRCs), MAPK gene mutation status, surface area of the primary tumor (as a marker of proliferation), and expression on RASAL2." (PMID 36790221, 2023). "However, previous studies also suggested RASAL2 as a tumor suppressor." (PMID 36159573, 2022). "However, with extensive research, RASAL2 was found to be upregulated in triple-negative and oestrogen-receptor negative breast cancers and was associated with tumour invasion, metastasis, and poor prognosis." (PMID 35668070, 2022). "In addition to its role in tumorigenesis, RASAL2 induced tumor invasion and metastasis." (PMID 30037330, 2018). "Furthermore, knockdown of RASAL2 significantly shortened the survival of tumor-bearing mice." (PMID 25216515, 2014).
tumor (continued). "Furthermore, RASAL2 depletion in SK-OV-3 cells significantly boosted tumor formation in vivo." (PMID 25216515, 2014). "This RASAL2-AKT-ETS1/VEGFA signaling axis orchestrates proangiogenic reprogramming, thereby potentiating tumor vascularization and progression in BCa." (PMID 40361412, 2025). "In TNBC cells and patient tumours, we observed that immunofluorescence staining of BCL2 overlapped with RASAL2, suggesting subcellular co-localisation of the two proteins." (PMID 39890967, 2025). "In keeping with the oncogenic propensity of RASAL2 in TNBC, we previously reported our observation that RASAL2 was overexpressed in the pre-treatment TNBC tumours of patients who had the worst treatment outcome following platinum-based chemotherapy." (PMID 39890967, 2025). "In summary, we found that the expression of RASAL2 increased in PDAC as compared to normal pancreatic tissues, promoted tumor cell proliferation, migration and invasion, and high expression of RASAL2 predicted a poor prognosis in PDAC patients." (PMID 35844783, 2022). "We further used DAVID to search for those genes from the predicted target genes that are related to tumor, and found the target genes of LYN, RASAL2, FZD4, and GNG2 for further study." (PMID 35174106, 2022). "RASAL2 is a member of the RAS-GAP family, but previous studies have revealed that its role in different tumours is inconsistent." (PMID 35668070, 2022). "The pro-proliferation and pro-migration effects of Rasal2 on PASMC are also in accordance with its role in promoting the progress and metastasis of several tumor cells." (PMID 35044284, 2022). "Similar to this observation, compared to that of RASAL2-NLS-WT, RASAL2-MUT more obviously abrogated the tumour-promoting function of IPO5 in vitro and in vivo, as indicated by colony formation, transwell experiments and subcutaneous tumourigenicity." (PMID 31288861, 2019). "Upregulation of RASAL2 mRNA in CRC was validated independently in the Hong Kong local cohort (P < 0.01), Gene Expression across Normal and Tumor tissue (GENT) (GSE20916, P < 0.01 and GSE21510, P < 0.01) and The Cancer Genome Atlas (TCGA) (P < 0.05)." (PMID 30037330, 2018). "In this study, we demonstrated that RASAL2, a RAS GTPase-activating protein, played a tumor-suppressive role in RCC by targeting tumor angiogenesis." (PMID 30158581, 2018). "In this study, we demonstrate RASAL2, a RAS GTPase-activating protein (RAS GAP), acts as a tumor suppressor in BCa." (PMID 28182001, 2017). "Our study revealed that QRHXF could inhibit tumor growth, and this effect of QRHXF may involve PDE3A, RASAL2, SERPIB5, and UTG1A4." (PMID 36159573, 2022). "In conclusion, this study revealed that QRHXF could inhibit tumor growth in an A549 xenograft mouse model, and the target genes of QRHXF may include PDE3A, RASAL2, SERPIB5, and UTG1A4." (PMID 36159573, 2022). "As compared with negative control cells, RASAL2 overexpression increased tumor cell viability and the clonogenicity." (PMID 35844783, 2022). "First, RASAL2 expression was higher in PCa tumour and metastatic lymph node tissues than in matched adjacent nontumor tissues and was associated with higher PCa tumour stage, Gleason score and poorer prognosis." (PMID 35668070, 2022). "In nude mouse models, RASAL2-overexpressing tumor cells and negative control cells were injected into flanks subcutaneously or tail vein intravenously." (PMID 35844783, 2022). "In our established PCa cell lines, we observed that RASAL2 might be involved in regulating the PI3K/AKT pathway and affected the G1-S phase transition in tumour cells." (PMID 35668070, 2022). "The results showed that RASAL2 protein expression levels were higher in PCa tumour and metastatic lymph node tissues than in nontumor tissues." (PMID 35668070, 2022). "Therefore, RASAL2 increased TIAM1 expression and promoted the malignancy of tumor cells by upregulation of YAP1." (PMID 35844783, 2022).
tumor (continued). "Using publicly available TCGA methylation 450 data, we found a negative correlation between RASAL2 methylation and RASAL2 mRNA, and a higher RASAL2 methylation was detected in tumor tissues compared to adjacent normal tissues." (PMID 30158581, 2018). "Interestingly, RASAL2, a GAP, has been identified as an oncogene promoting tumor production and metastasis in various cancers, However, rather than suppressing tumors, RASAL2 facilitates mesenchymal invasion and metastasis." (PMID 40104500, 2025). "In conclusion, INPP5B is a potential tumor suppressor gene that has not yet been experimented, and RASAL2 may have a bidirectional effect on tumors, however, both require further study." (PMID 34430085, 2021).
cancer (20 papers, 2014 to 2025). A tumor composed of atypical neoplastic, often pleomorphic cells that invade other tissues. "Pharmacogenomic analysis of human cancer cell lines revealed that RASAL2 was broadly associated with resistance to classic DNA-damaging agents." (PMID 39890967, 2025). "These genes, including Smc2, Mcm3, Ccnd1, Rasal2, Mcm6, and Mad2l1, are linked to cancer progression and metabolic regulation." (PMID 39272991, 2024). "The RAS protein activator like 2 (RASAL2) negatively regulates RAS proto-oncogene which is activated by high mutation rate in cancer." (PMID 34966481, 2021). "While these and other studies have begun to clarify the oncogenic implications of RASAL2, its molecular mechanism in mediating therapeutic responses in any cancer contexts remains undefined." (PMID 39890967, 2025). "RASAL2 also suppresses cancer progression via the RAS-ERK pathway 22, phosphoinositide 3-kinase (PI3K)/AKT/mechanistic target of rapamycin (mTOR) signaling pathway 7, nuclear factor (NF)-κB pathway 7, and ERK/mitogen activated protein kinase (MAPK) pathway." (PMID 35844783, 2022). "H. pylori infection activates ras protein activator like 2 (RASAL2) by β-catenin to promote the proliferation of cancer cell." (PMID 35844804, 2022). "It is believed that RASAL2 can promote cancer progression by activating the oncoprotein RAC1, a RAS-related small GTPase." (PMID 34966481, 2021). "RASAL2 was reported to exhibit pro-tumourigenic or anti-tumourigenic effects in different types of cancer." (PMID 31288861, 2019). "Recent research reported that RASAL2 suppressed cancer progression via the Hippo signaling pathway, WNT/β-catenin pathway, and RAS signaling pathway." (PMID 31799194, 2019). "RASAL2 plays an important role in the invasion and metastasis of some cancer cells, which regulates the action of the cancer cells." (PMID 31799194, 2019). "In most cancers, RASAL2 is inhibited and downregulated so that the cancer cells can escape from its preventative effects." (PMID 31799194, 2019). "RASAL2 plays inconsistent roles in different cancers, including promoting invasion and metastasis of some cancer cells and not others." (PMID 31799194, 2019). "However, RASAL2 also functions as an oncogene in various cancers via the Hippo signaling pathway 16, WNT/β-catenin pathway 25, and RAS signaling pathway." (PMID 35844783, 2022). "The RASAL2 gene is commonly inactivated by epigenetic mechanism in malignant tumors." (PMID 34966481, 2021). "RASAL2 inhibits angiogenesis of cancer cells via p-AKT/ETS proto-oncogene 1 (ETS1) signaling." (PMID 31799194, 2019). "In this review, we summarize the latest findings regarding RASAL2 in cancers, which may be important and useful in clinical practice." (PMID 31799194, 2019). "In human cancers, RASAL2 may exhibit pro- or anti-oncogenic behavior depending on the type of stimulus or cell context, which is quite interesting." (PMID 31799194, 2019). "Thus, what makes RASAL2 thought-provoking is its ability to exert opposite effects in different cancers, which is different from most regulators, which usually exhibit either pro- or anti-oncogenic behavior." (PMID 31799194, 2019). "As seen, the role of RASAL2 in cancer is still controversial, and the expression and function of RASAL2 in RCC are still completely unknown." (PMID 30158581, 2018). "RASAL2 also participates in the regulation of cancer cell invasion and migration." (PMID 25216515, 2014). "Furthermore, given RASAL2's role in tumourigenesis in other cell types, we speculate that it may represent a target for intervention in a broader range of cancers." (PMID 36790221, 2023). "However, recent researches indicate that the regulation of Rasal2 on cancer is multiple." (PMID 35044284, 2022).
cancer (continued). "Future studies to investigate RASAL2 expression in PCa tissues and examine relationship with clinical cancer stage as well as histological grade are warranted as RASAL2 has the potential as a novel prognostic marker and a therapeutic target for PCa and other cancers." (PMID 34966481, 2021). "We discussed the specific functions and mechanisms of RASAL2 in different kinds of cancer cells (including its inhibition of invasion, metastasis and angiogenesis and its opposite effects), which may provide new directions for cancer research and treatments." (PMID 31799194, 2019). "However, RASAL2 also functions as an oncogene in various cancers via the RAS-ERK pathway, phosphoinositide 3-kinase (PI3K)/AKT/mechanistic target of rapamycin (mTOR) signaling pathway, nuclear factor (NF)-κB pathway, and ERK/mitogen activated protein kinase (MAPK) pathway." (PMID 31799194, 2019). "As a member of Gas-Gap gene, RASAL2 is involved in the hydrolysis of RAS-GTP to RAS-GDP and abnormal expression in human cancers." (PMID 35844783, 2022). "In the present study, we discovered that RASAL2, a RAS-GTPase-activating protein, acted as an oncogene to regulate cancer cell proliferation and the cell cycle and contributed to tumorigenesis via the PI3K/AKT/cyclin D1 pathway." (PMID 35668070, 2022). "MiR-203 is a cancer suppressor that interacts with different genes involved in hepatocarcinogenesis, such as EZH2 and BMI1, SURVIVIN, RASAL2, ADAM9, and MMP2." (PMID 31073374, 2019). "RASAL2 also downregulates sex-determining region Y-box 2 (SOX2) and CD44, which are indicators of cancer stemness, by inhibiting the ERK/MAPK pathway." (PMID 31799194, 2019). "So far, the majority of research regarding RASAL2 was focused on EMT and invasion contributing to cancer metastasis." (PMID 30158581, 2018). "RASAL2 mRNA expression was higher in CRC cell lines than in normal colons, and significantly higher in advanced stage cell lines [American joint committee on cancer (AJCC) stage III and IV] than in early stage ones (AJCC stage I and II) (P < 0.05)." (PMID 30037330, 2018).
prostate (1 paper, 2021). "In our study, it appears that there is a crosstalk between RASAL2 and TNFα signals in prostate carcinogenesis." (PMID 34966481, 2021). "Ingenuity Pathway analysis showed crosstalk of RASAL2 and several genes including TNFα which is an important signaling intermediate in prostate carcinogenesis." (PMID 34966481, 2021).
RASAL2 also shares sentences with these, for which no sentence is quoted: craniosynostosis (1 paper); Kaposi's sarcoma (1); kidney cancer (1); metabolic disorder (1); mucopolysaccharidosis (1); Obesity (1); renal carcinoma (1); respiratory diseases (1); thyroid cancer (1).